SMO (smoothened, frizzled class receptor)
Diseases named in the same sentence as SMO in open-access papers (continued):
Sharing a sentence is not in itself a finding about the gene and the disease.
lung carcinoma (25 papers, 2012 to 2025). "In addition, EGFR-mutated lung cancer cells resistant to EGFR TKIs also harbor SMO amplification along with Met activation." (PMID 29581874, 2018). "RT-qPCR demonstrated that GLI1 or SOX2 overexpression remarkably stimulated the SMO/GLI1/SOX2OT/SOX2 axis in lung cancer cells." (PMID 37149646, 2023). "Our observations suggest that SMO and Hedgehog signaling are important for tumorsphere formation in lung cancer." (PMID 32033067, 2020). "Lung cancer cells transfected with SMO-specific siRNA showed a 40% reduction in tumorsphere formation." (PMID 32033067, 2020). "In lung cancer studies, SMO amplifications and subsequent activation of the hedgehog pathway confer resistance to anti-EGFR drugs." (PMID 31565188, 2019). "Moreover, we unveiled Solamargine exhibited lung cancer suppression by targeting SMO in the hedgehog signaling pathway." (PMID 36034794, 2022). "Various SMO inhibitors are used in clinical investigations for lung cancer." (PMID 28105432, 2016). "Although further investigations should be done to verify whether SMO is the key target in lung cancer, our data is of great value forpromising combination therapy and would provide a possible solution for the improvement of individualized therapeutic and prognosis of lung cancer in the coming days." (PMID 36034794, 2022). "Finally, we show that the H460 SP cells preferentially express ABCG2 as well as SMO, a critical mediator of the Hedgehog (HH) signaling, which seems to play an important role in H460 lung cancer cells as its blockage using Cyclopamine greatly inhibits cell-cycle progression." (PMID 22428030, 2012). "Prior studies have shown that targeting key points in the Hedgehog pathway, such as SHh, SMO, and GLI, can suppress lung cancer cell proliferation, enhance lung cancer cell apoptosis, and enhance drug sensitivity in drug-resistant lung cancer cells." (PMID 41444284, 2025). "Initially, using the lung cancer dataset, it was identified in VEGFC and proteins from the treatment datasets: RXRA, PPARG, and SMO." (PMID 40334012, 2025). "Combination treatment with sulforaphane and gefitinib dose-dependently inhibits the expression of SHH, SMO, and GLI1 and suppresses the proliferation of gefitinib-resistant lung cancer cells through the SHH signaling pathway." (PMID 36770689, 2023). "In the cisplatin-resistant lung cancer cell lines NCI-H1299 and NCI-H460, solamargine inhibited cell proliferation and promoted apoptosis by targeting SMO and thereby inhibiting the HH pathway." (PMID 36770689, 2023). "The correlation of SMO, GLI1, and SOX2 expression with poor prognosis in lung cancer has been demonstrated." (PMID 37149646, 2023). "We performed data mining using the University of California Santa Cruz genome browser and Gene Expression Database of Normal and Tumor Tissues 2 (GENT2) and confirmed overexpression of SMO, GLI1, SOX2, and SOX2OT in lung cancer samples." (PMID 37149646, 2023). "RT-qPCR and immunoblotting revealed that SMO, GLI1, and SOX2 were more actively transcribed and translated in lung cancer spheroids than in parental cells." (PMID 37149646, 2023). "The lack of SMO expression in CSCs may partly explain the lack of benefit in lung cancer associated with the addition of SMO inhibitor to chemotherapy regimens, but there is yet to be a study to elucidate the importance of SMO/GLI in promoting chemoresistance in the context of CSC in lung cancer." (PMID 34572373, 2021). "Alteration in PTCH expression does not affect oncogenic functions of Hedgehog cascade driven by SHH, SMO, and GLI1 in lung cancer cells." (PMID 28507311, 2017). "Therefore, SMO inhibitors may be a better option for lung cancer therapy in the future." (PMID 28105432, 2016). "The data disclose a new GLI1 stimulation pathway independent of the SHH/PTCH/SMO cascade and offer new insights into the stemness-related malignancy of lung cancer cells." (PMID 37149646, 2023).
lung carcinoma (continued). "We next analyzed the expression levels of canonical SHH signaling components—such as PTCH1, PTCH2, SMO, SUFU, and GLI1 proteins—in cultured human lung cancer cells (H1299, A549, HCC827, and H1975) and normal human lung fibroblasts (MRC-9 and WI38) by western blot analysis." (PMID 31783569, 2019). "Two SMO inhibitors GDC-0449 (GDC) and BMS-833923 (BMS) for downregulation of SHH signaling was applied to explore whether activation of SHH pathways is involved in growth and clonal expansion of lung cancer cells." (PMID 28507311, 2017). "However, previous studies showed that the proliferation of lung cancer cell lines H520 and A549 could not be affected by exogenous shh or SMO inhibitor (GDC0449) but could be inhibited by GLI protein inhibitor (GANT61)." (PMID 26936993, 2016).
glioblastoma (21 papers, 2015 to 2025). The most malignant astrocytic tumor (WHO grade IV). "a., encoded by circ-SMO was critical for Hedgehog signaling, driving glioblastoma tumorigenesis, and acted as a novel target for glioblastoma treatment." (PMID 39519039, 2024). "Our study reveals that SMO-193a.a., a novel protein encoded by circular SMO, is critical for Hedgehog signaling, drives glioblastoma tumorigenesis and is a novel target for glioblastoma treatment." (PMID 33446260, 2021). "In glioblastomas, the abnormal activation of SHH signaling typically by mutation in Patched1 and/or activating mutations in SMO leads to the transformation of adult stem cells into glioblastoma stem cells." (PMID 32290213, 2020). "In another instance, circRNA circ-SMO was found to encode the SMO-193a.a peptide, a key component of the Hedgehog signaling pathway that fuels glioblastoma tumorigenesis and presents a promising therapeutic target for glioblastoma." (PMID 40568595, 2025). "For instance, circ-SMO is significantly upregulated in glioblastoma (GBM) and activates the Hedgehog pathway to promote tumorigenesis through encoding a novel protein SMO-193a.a." (PMID 35236349, 2022). "Among them, SMO was highly expressed in glioblastoma multiforme (GBM), KIRP, NSCLC, liver hepatocellular carcinoma (LIHC), and prostate adenocarcinoma (PRAD) compared with normal tissue." (PMID 36405701, 2022). "Hypomethylation of SMO promoter has also been detected in other cancers, including prostate, kidney, glioblastoma, and ovarian cancer cell lines, and a positive correlation was identified between SMO and GLI2 transcript levels." (PMID 34572373, 2021). "SMO inhibitors such as vismodegib, trametinib, and glasdegib have been under investigation for glioblastoma." (PMID 32290213, 2020). "The expression levels of circ_COL1A2, circ_PTN, circ_VCAN, circ_PLOD2, circ_SMO, circ_CLIP2, circ_GLIS3, and circ_EPHB4 in glioblastoma (GBM) are significantly higher than those in normal tissues." (PMID 30064463, 2018). "Eight circRNAs, including circ_COL1A2, circ_PTN, circ_VCAN, circ_SMO, circ_PLOD2, circ_GLIS3, circ_EPHB4, and circ_CLIP2 showed significantly higher expression in glioblastoma (GBM) than in normal tissues." (PMID 28969099, 2017). "For instance, SMO inhibitors have also shown to increase the effects of the alkylating agent temozolomide in glioblastoma xenograft models, mostly acting on the CSC population that is spared by temozolomide alone (Refs 75, 290)." (PMID 25660620, 2015). "Self-renewal, survival and tumourigenicity of CD133+ glioblastoma CSCs require SMO and GLI1 activity, as shown by their inhibition with cyclopamine and RNA interference (Refs 75, 84)." (PMID 25660620, 2015). "In glioblastoma harboring PI3K/mTOR activation due to PTEN deficiency, combined inhibition using the SMO inhibitor LDE225 and the PI3K inhibitor BKM120 was necessary to reduce cell viability and inhibit tumor growth." (PMID 25749378, 2015). "Thus, in PTEN-deficient glioblastomas, GLI1 expression is driven by both SMO-dependent canonical Hh and PI3K pathways." (PMID 36010600, 2022). "Also, GLI1 mRNA transcription was decreased with the SMO inhibitor, sonidegib, in PTEN-deficient glioblastoma." (PMID 36010600, 2022). "is more specifically expressed in glioblastoma than SMO and is relevant to Gli1 expression." (PMID 33446260, 2021). "Currently, there are three ongoing clinical trials based on SMO inhibition for glioblastomas." (PMID 32290213, 2020). "Similarly, inhibition of SMO reduces epithelial–mesenchymal transition and self-renewal of glioblastoma-initiating cells (Ref." (PMID 25660620, 2015). "SMO inhibitors, vismodegib (GDC-0449), sonidegib (NVP-LDE225) and saridegib (IPI-926), have been approved by the FDA for the treatment of glioblastoma and base cell carcinoma or for clinical trials in the treatment of pancreatic, breast and colon cancer." (PMID 33440657, 2021).
glioblastoma (continued). "Previous studies showed that hsa-miR-326 inhibited SMO expression in glioma cancer and CD34(+) chronic myeloid leukemia cells and acted as a tumor suppressor miRNA by inhibiting the PI3 kinase pathway in glioblastomas." (PMID 30777071, 2019). "Hh signaling appears to be active in glioblastoma multiforme (GBM)-derived neurospheres and glioma stem cell cultures (gliomaspheres), as they express GLI1, PTCH1, SMO and SHH." (PMID 26270676, 2015). "Previous studies have showed that increasing ARL13B in glioblastoma cells promoted ciliary SMO accumulation, independent of exogenous SHH addition." (PMID 37830570, 2023). "However, the efficacy of SMO inhibitors in other solid carcinoma may not be as effective as in glioblastoma or base cell carcinoma due to activation of the non-canonical Hh signaling pathway or other oncogenic signaling pathways." (PMID 33440657, 2021).
Gorlin syndrome (16 papers, 2013 to 2023). "Mutations of SMO can be found in keratocysts in Gorlin-Goltz syndrome, as well as in sporadic keratocysts." (PMID 24716509, 2014). "Following the discovery of a germline mutation in the patched homolog 1 (PTCH1) gene in basal cell nevus syndrome, mutations in genes associated with the HH signaling pathway, including PTCH1 and smoothened homolog (SMO), were discovered in sporadic BCCs." (PMID 35870014, 2023). "This is often caused by loss of function mutations in the PTCH gene that produce a protein unable to prevent SMO from activating the pathway, as first demonstrated by patients with nevoid basal cell carcinoma syndrome, or Gorlin syndrome." (PMID 36091167, 2022). "Hp is physiologically responsible of normal embryo development, butin patients with Gorlin syndrome, PTCH mutations cause unrestrained signaling through SMO, with high rate of tumor, especially BCCs." (PMID 34639065, 2021). "In Gorlin syndrome, germline inactivation of one copy of the PTCH1 gene followed by somatic loss of the second allele result in loss of SMO suppression and hence constitutive overexpression of the HH signal." (PMID 34359772, 2021). "Activating or loss of function mutations in the HH pathway genes SMO and PTCH1 occur in human gastric tumors, sporadic BCC, medulloblastoma, nevoid basal cell carcinoma syndrome (NBCCS), and colorectal cancer." (PMID 33494284, 2021). "Given the high discontinuation rates of oral SMO antagonists, a topical inhibitor, patidegib, has also been trialed with reduced disease burden in patients with Gorlin syndrome." (PMID 34359772, 2021). "Rare causes are PTCH2 and SMO mutations: a missense mutation in PTCH2 was disclosed in a Chinese family, and a SMO mutation in a single case with a segmental basal cell nevus syndrome." (PMID 29552546, 2018). "We previously performed whole exome and targeted re-sequencing of 58 sporadic and Gorlin’s Syndrome BCC samples and found expected mutations in PTCH1 and SMO in accordance with our previous publications." (PMID 28030567, 2016). "Patidegib exhibits its pharmacological effect by inhibiting SMO, and received approval as Orphan Drug Designation and Breakthrough Therapy Designation as topical gel in Gorlin syndrome both by FDA and EMA’s Committee for Orphan Medicinal Products in the EU in 2018." (PMID 34639065, 2021). "It was first characterized by identification of a germ line mutation in the patched homolog 1 (PTCH1) gene in basal cell nevus syndrome, which was then reinforced by the discovery of mutations of PTCH1, smoothened homolog (SMO), and other genes related to the HH signaling pathway in sporadic BCC." (PMID 31355203, 2019).
acute myeloid leukemia (14 papers, 2016 to 2026). Acute myeloid leukemia (AML) is a group of neoplasms arising from precursor cells committed to the myeloid cell-line differentiation. "In 2018, a great advance came with the FDA approval of another SMO inhibitor glasdegib (aka PF-04449913) for treatment of patients with acute myeloid leukemia (AML)." (PMID 37213270, 2023). "Three SMO inhibitors, vismodegib, sonidegib and glasdegib, have been approved for the treatment of locally advanced and metastatic basal cell carcinoma and for acute myeloid leukemia, respectively." (PMID 34439381, 2021). "One inhibitor targeting the pathway via the protein Smoothened (SMO), glasdegib, has been approved by the FDA for use with a low dose cytarabine regiment in some high-risk acute myeloid leukemia patients (AML)." (PMID 36091167, 2022). "The Hedgehog (HH) signaling pathway is aberrantly activated in many of these diseases, and glasdegib, a Smoothened (SMO) antagonist and HH pathway inhibitor, has recently been approved for the treatment of acute myeloid leukemia (AML)." (PMID 34638372, 2021). "Another SMO antagonist glasdegib, also known as PF-04449913, is being tested in patients with acute myeloid leukemia (AML) and in combination with nucleoside analog Azacitidine for other hematologic malignancies such as chronic myelomonocytic leukemia." (PMID 26988232, 2016). "Clinically used SMO antagonists include vismodegib and sonidegib, indicated for BCC, and glasdegib, used in acute myeloid leukemia (AML) 102-104." (PMID 41522355, 2026). "For refractory acute myeloid leukemia (AML), agents that promote β- catenin degradation; for basal cell carcinoma, hedgehog inhibitors; and for SHH-subtype medulloblastoma and newly diagnosed AML, SMO inhibitors have been tried." (PMID 32580319, 2020). "Three SMO antagonists were recently approved by the US FDA, Vismodegib (Erivedge®) in 2012 for BCC, Sonidegib (Odomzo®) in 2015 for BCC and Glasdegib (DaurismoTM) in 2018 for acute myeloid leukemia (AML)." (PMID 31539380, 2019). "A transcriptomic analysis of 772 GPCRs in 148 acute myeloid leukemia (AML) samples, encompassing different subgroups, identified ADGRG6 as one of 19 down‐regulated GPCRs, with others including the closely related ADGRG1 and SMO." (PMID 33735533, 2021).
gastric cancer (13 papers, 2013 to 2024). A primary or metastatic malignant neoplasm involving the stomach. "In this study, the identified mutation, 23L_24GinsL, lies in the signal peptide region of SMO and has been detected in two cases of human gastric cancer {Wang, 2013 #657}." (PMID 23826113, 2013). "Furthermore, our data revealed that Gal-1 modulated the non-canonical Hh pathway by increasing the transcription of glioma-associated oncogene-1 (Gli-1) via a Smoothened (SMO)-independent manner, and that upregulation of Gal-1 was strongly associated with gastric cancer metastasis." (PMID 27835885, 2016). "About 1.44% of GC patients have altered SMO, which leads to its constitutive activation 8, and Hh inhibitors suppressed tumor proliferation and invasion of gastric cancer in preclinical studies 9-11." (PMID 35281856, 2022). "SMO shRNA or inhibitors can significantly suppress the spheroid formation and tumor growth of gastric cancer cell lines." (PMID 32962123, 2020). "This means HER2 regulates its main downstream pathway PI3K-Akt-mTOR34,35.Then we added rapamycin to gastric cancer cells, the expression level of p-p70S6k and Gli1 decreased while SMO remained unchanged." (PMID 29321573, 2018). "After adding trastuzumab to gastric cancer cells, the expression level of Gli1 decreased while SMO remained unchanged." (PMID 29321573, 2018). "Evidently, p-AKT knockdown decreased GLI1 protein expression without affecting SMO levels, and this was associated with depressed growth and migration and enhanced cisplatin sensitivity of gastric cancer cell lines." (PMID 34572373, 2021). "SMO overexpression upregulates 5-Bromo-2′-Deoxyuridine (BrdU) in gastric cancer cells." (PMID 31979397, 2020). "In paclitaxel-treated gastric cancer cells, overexpression of SMO could reduce activated caspase 3, thus decreasing cancer cell death." (PMID 31979397, 2020). "To identify whether SMO or Gli-1 are directly regulated by Gal-1, we treated Gal-1-overexpressing gastric cancer cell lines with cyclopamine (a SMO antagonist) or a siRNA specific to SMO and Gli-1 in the presence of rGal-1." (PMID 27835885, 2016). "This SMO antagonist could affect the maintenance and other properties of gastric cancer stem cells." (PMID 31979397, 2020). "CD44 with overexpression of HH/SMO pathway genes and some self-renewal marker proteins (SOX2, OCT4 and NANOG) in several gastric cancer cell lines were found." (PMID 32962123, 2020). "Other researchers found that SMO or GLI1 inhibitors impair the migration and invasion of gastric cancer cells." (PMID 31979397, 2020). "Taken together, these data suggest Gal-1 increases gastric cancer cell invasion and promotes the EMT in a SMO-independent manner." (PMID 27835885, 2016). "Intriguingly, loss of Gal-1 in gastric cancer cells resulted in a lack of SHH expression, leading to Hh inactivation, which downregulated SMO and Gli-1." (PMID 27835885, 2016). "Staining of gastric cancer patient samples and patient cell line derived-xenografts showed that the CD44-expressing population of stem-like cells overexpresses Hh proteins; consequently, blocking Hh signaling with SMO inhibitor vismodegib reduced the colony formation ability of these cells." (PMID 26988232, 2016). "Accordingly, we concluded that SMO-independent activation of Gli-1, i.e., non-canonical Hh signaling, was at least partially responsible for Gal-1-induced EMT and invasion in gastric cancer cells." (PMID 27835885, 2016).